STAT1 (signal transducer and activator of transcription 1)
Diseases named in the same sentence as STAT1 in open-access papers (continued):
Sharing a sentence is not in itself a finding about the gene and the disease.
autoimmune disease (57 papers, 2005 to 2025). A disorder resulting from loss of function or tissue destruction of an organ or multiple organs, arising from humoral or cellular immune responses of the individual to their own tissue constituents. "The STAT1 GOF mutation is also commonly associated with autoimmune diseases, such as autoimmune thyroid disease, autoimmune agranulocytosis, autoimmune hepatitis, vitiligo, type I diabetes, and systemic lupus erythematosus-like disease." (PMID 36225936, 2022). "The previous strategies to block STAT1 functions to treat autoimmune diseases inhibit Th1 cell activity but simultaneously cause hyper-activation of Th17 cells." (PMID 36591260, 2022). "In the case of STAT1 deficiency, while several groups have reported a reduced expansion of Stat1−/− T cells in animal models of autoimmune disease and GvHD, the mechanistic basis for this reduction was unclear." (PMID 30796216, 2019). "There is emerging evidence of general IFN signature in autoimmune disorders as well as a direct pathogenic role of overexpression and phosphorylation of STAT1 and STAT5 in mice and humans." (PMID 26525134, 2015). "IFNγ is a cytokine associated with a number of autoinflammatory and autoimmune diseases, due to its role in Th1 cell stimulation, differentiation, and function via STAT1 and STAT4 pathways." (PMID 24405805, 2014). "The STAT1 gene is located adjacent to STAT4 suggesting it is also a candidate susceptibility gene for autoimmune disease." (PMID 23990947, 2013). "Our previous work had demonstrated that STAT1-deficiency dramatically increases the incidence of autoimmune disease." (PMID 21949815, 2011). "Others have also demonstrated that STAT1-deficient mice have an increased susceptibility to autoimmune disease that is linked to the presence of a reduced number of Tregs." (PMID 19889125, 2010). "Nishibori and colleagues demonstrated impaired development of Treg cells in naive signal transduction and activators of transcription (STAT)-1-deficient mice, associated with an increased susceptibility to autoimmune disease." (PMID 15743488, 2005). "The present findings provide a novel understanding of the dynamics of STAT1 activation and will be useful to develop novel and hopefully targeted (i.e. favouring individuals with particular polymorphisms) therapies for T1D and other autoimmune diseases." (PMID 40162226, 2025). "It is also known that STAT1-deficient mice are highly susceptible to autoimmune disorders, and given that AMD may be considered an autoimmune disease, preserving STAT1 activation may be necessary for mitigating AMD progression." (PMID 37273909, 2023). "It is known that STAT1-deficient mouse are highly susceptible to autoimmune disorders, thus STAT1 activation by IFN-γ may be important in mitigating AMD progression." (PMID 27266510, 2016). "IL-27 is a unique cytokine with reported immunostimulatory and immunosuppressive effects that are exerted through STAT1/3-dependent cascades and thought to be involved in various autoimmune diseases including T1D." (PMID 41027725, 2025). "Among them, STAT1 GOF mutations represent the most prevalent genetic cause of inherited CMC as well as various infectious and autoimmune diseases along with cerebral aneurysms and carcinomas with a poor outcome." (PMID 38327523, 2024). "Recently, JAKi have been used to regulate pathological inflammatory responses in patients with various autoimmune diseases, including STAT1 GOF." (PMID 38578320, 2024). "Translating well into the clinical manifestation, enhanced IFN signaling plays a role in promotion and advancement of autoimmune diseases, and in fact, STAT1 GOF manifestations have been likened to type I interferonopathies." (PMID 37358695, 2023). "Considering the results from our therapeutic strategy targeting STAT1 in Th1 cells or Th17 cells, ndSTAT1-TMD can be an effective and new therapeutic reagent for treating various autoimmune diseases associated with pathogenic Th1 and Th17 cells." (PMID 36591260, 2022).
autoimmune disease (continued). "STAT1 is involved in cell differentiation, function and apoptosis processes, as well as tumor, chronic inflammation and autoimmune diseases." (PMID 34017248, 2021). "STAT1 and STAT3, which were found to be significantly dampened by P4, have been implicated in the disease pathogenesis of several autoimmune diseases." (PMID 34054852, 2021). "In other autoimmune diseases, tofacitinib was found to inhibit the phosphorylation of STAT1 and STAT3 in psoriatic arthritis FLS as compared to vehicle control." (PMID 31181818, 2019). "A line of clinical reports have shown that “gain-of-function” mutations in signal transducer and activator of transcription 1 (STAT1) affect Th cell functions and alter susceptibility to autoimmune diseases and infections with microbes, including viruses." (PMID 28874814, 2017). "Combined with the control of the nuclear translocation of IRF7, the modulation of STAT1 transcription and phosphorylation, Bank1 contributes to IgG production during development of autoimmune disease." (PMID 27228057, 2016). "Even though all IFNs utilize STAT1 as a signaling mediator, type I and II IFNs exert opposing effects on the progression of the demyelinating, T cell-mediated autoimmune disease multiple sclerosis (MS)." (PMID 21949815, 2011). "Notably, STAT1, which was identified in both dmGWAS and EW_dmGWAS, is a key regulator in both autoimmune diseases and cancer progression." (PMID 40429780, 2025). "Neutrophil products or impaired functions are involved in immunopathology of several autoimmune diseases; therefore, we suggest that abnormally activated neutrophils may contribute to the autoimmune features of STAT1 GOF CMC." (PMID 37358695, 2023). "However, neutrophils and their products have been implicated in various human autoimmune diseases, such as systemic lupus erythematodes (SLE), psoriasis, or type I diabetes mellitus (T1D); therefore, an investigation of their role in STAT1 GOF is warranted." (PMID 37358695, 2023). "Stat1-deficent mice develop aggravated Th17-mediated autoimmune diseases." (PMID 35313878, 2022). "Interestingly, monocytes have been associated with various autoimmune diseases or immunodysregulatory phenomena and previous research showed that STAT1 GOF mutations affect the JAK/STAT1-mediated signaling in CD14+ monocytes." (PMID 36172362, 2022). "STAT1 related regulation of IL-31RA may link this pathway also with autoimmune diseases such as systemic sclerosis, dermatomyositis and lupus erythematosus." (PMID 33644104, 2021). "It is also known that STAT1-deficient mouse are highly susceptible to autoimmune disorders and given that AMD may be considered an autoimmune disease, preserving STAT1 activation by IFN-γ may be important in mitigating AMD progression." (PMID 24977104, 2013). "No GWAS on autoimmune diseases have identified STAT1 as a risk allele." (PMID 30061896, 2018). "STAT1 overexpression and GATA3 overexpression in FOXP3+ Tregs have been reported in autoimmune diseases." (PMID 38774869, 2024). "From the combined databases in this study, the mRNA levels of STAT1 and OAS1 were increased in IDC while reduced in SLE manifesting the opposite expression tendency across cancer and autoimmune disease." (PMID 36765396, 2023). "Enhanced production of NETs and ROS, detected by the STAT1 GOF neutrophils, has been reported to exaggerate classic autoimmune diseases, such as SLE, rheumatoid arthritis, systemic sclerosis, or T1D." (PMID 37358695, 2023). "STAT1 GOF patients frequently experience other severe invasive/opportunistic infections, and one third also develop autoimmune disease." (PMID 37275873, 2023). "The expression levels of STAT1 and OAS1 manifest the opposite expression tendency across cancer and autoimmune disease." (PMID 36765396, 2023). "All STAT family members (STAT1, STAT2, STAT3, STAT4, STAT5A, STAT5B, and STAT6) are related to autoimmune diseases." (PMID 35204186, 2022).
autoimmune disease (continued). "In inflammatory and autoimmune diseases, the transcriptional activation of the STAT pathway is regulated via the transcription factors STAT1/3/5/6." (PMID 35625761, 2022). "WhileHDAC3 powerfully regulates STAT1 activity in RA-FLS, indicating HDAC3 as a potential therapeutic target in the treatment of RA and type I IFN-driven autoimmune diseases." (PMID 30884802, 2019). "STAT1, STAT2, and IRF9 amplify the JAK-STAT signaling pathway to enhance the IFN response, and the JAK-STAT pathway transduces intracellular signals for various cytokines, which is crucial for the pathogenesis of autoimmune diseases." (PMID 41181153, 2025). "In addition, MSCs suppress Th17 cell differentiation through IFN-γ-mediated STAT1 activation, which upregulates SOCS3 and inhibits STAT3 signaling, ultimately exerting immunomodulatory effects in autoimmune diseases, including psoriasis." (PMID 40906403, 2025). "Additionally, we predicted and verified the STAT1 as the possible TF of the ISG15 and CD53 in the two autoimmune diseases." (PMID 39136821, 2024). "Investigations into the commonalities between autoimmune diseases and cancer have highlighted the crucial role of the IFN-JAK-STAT signal related to STAT1 and OAS1, implying that OAS1 may play a significant role in immune homeostasis in both of these diseases." (PMID 37928544, 2023). "Regardless of the exact mechanism, Stat1 is undoubtedly an important target of GCs in many situations including autoimmune diseases." (PMID 36766792, 2023). "In addition, plasma treatment in keratinocytes also suppressed STAT1 and STAT3 activation, which are involved in chronic allergic inflammation and autoimmune diseases, respectively." (PMID 31534179, 2019). "The differential effects of IFN-γR/STAT1 signaling on endogenous and exogenous antigen presentation could provide further insight into the roles of the IFN-γ/STAT1 signaling pathway in the pathogenesis of GVHD, organ rejection, and autoimmune diseases." (PMID 36445781, 2023). "The miR-19a-3p/STAT1/IRF1 axis may be a potential target in macrophage polarization, and highlights a better comprehension for potential mechanism of pathogenesis and progression of diseases such as chronic inflammatory and autoimmune diseases." (PMID 34017248, 2021). "Also, in certain mouse models, the IFN-γ/STAT1 pathway mediates protective effects in autoimmune disease and arthritis, and lack of IL-4 and STAT6 suppresses arthritis." (PMID 27942004, 2016).
psoriasis (55 papers, 2009 to 2025). An autoimmune condition characterized by red, well-delineated plaques with silvery scales that are usually on the extensor surfaces and scalp. "For example, blocking the STAT1 function is known to suppress the activity of pathogenic Th1 cells and induce the hyperactivation of Th17 cells, thereby suppressing psoriasis caused by them." (PMID 37631075, 2023). "The IFN-γ, IL-17A and IL-22 are key pathogenic cytokines in psoriasis and one of the main mediators of cytokine signaling is STAT1." (PMID 33986690, 2021). "Similarly, enhanced STAT1 signaling has been associated with pathologies such as ischemia/reperfusion injury, unstable angina, celiac disease, and psoriasis." (PMID 40564127, 2025). "Taken together, our findings demonstrate that STAT1 signaling pathway is responsible for the increase of miR-17-92 cluster induced by cytokines in keratinocytes, which is possibly the mechanism underlying the upregulation of miR-17-92 cluster in psoriasis." (PMID 29752469, 2018). "STAT1 is another important regulator: its downregulation promotes STAT3 activation and IL-22 production, whereas activation of STAT1 suppresses skin inflammation in imiquimod-induced psoriasis models." (PMID 40906403, 2025). "STAT1 is a central transcriptional regulator of psoriatic inflammation and highly expressed in psoriasis lesions." (PMID 40243413, 2025). "In summary, the study identified a series of characteristic genes (DEFB103A, IFI16, OAS3, OASL, SAMD9, STAT1, etc.)that are highly related to the occurrence, treatment of psoriasis." (PMID 40560938, 2025). "A total of 5 genes (DEFB103A, OAS3, OASL, SAMD9, STAT1) were co-identified as characteristic genes in psoriasis progression and treatment." (PMID 40560938, 2025). "Evidence points to involvement of IFN-γ and IL-21, which activate STAT1 and Th17 cells, but IL-17 is minimally expressed in LP tissues compared to psoriasis." (PMID 40948686, 2025). "IL-17A is the key driver of the pro-inflammatory keratinocyte pathogenesis in psoriasis, along with a dominant IFNγ/STAT1 signature." (PMID 39843435, 2025). "Subsequently, WGCNA showed the hub genes (e.g., S100A12, CYCS, NOD2, STAT1, HSPA4, AIM2, MAPK7), which were significantly associated with clinical phenotype, PANoptosis signature, and identified immune response in psoriasis." (PMID 38125299, 2024). "There was significant enrichment of genes controlled by the transcription factors IKBKB (log2fold enrichment 6.361, Padj = 0.040) and STAT1 (log2fold enrichment 3.679, Padj = 0.040) in psoriasis uninvolved skin." (PMID 37137278, 2024). "A research on psoriasis pathogenesis revealed that STAT1 directly antagonized STAT3 and repressed IL-22 expression." (PMID 37391858, 2023). "The JAK/STAT3 and JAK/STAT1 signaling pathways play an important role in the development of psoriasis when triggered by IL-6 and IFN-γ, which are produced by dendritic cells and T-lymphocytes." (PMID 36838711, 2023). "Collectively, T-bet interacts with the STAT1 and perhaps the Notch pathways to regulate differentiation or warrant Th1 response in psoriasis." (PMID 37270497, 2023). "The purpose of this study is to evaluate the expression of certain cell cycle and STAT1/3 genes in psoriasis patients and to determine the types of comorbidities associated with these genes." (PMID 36497125, 2022). "Alternatively, the excessive activation of the STAT1 and NF-κB signaling pathways aggravated skin inflammation in psoriasis." (PMID 34641629, 2021). "Our results demonstrated that STAT1 emerges as a key target of both LV extract and its main bioactive component RA, through which they exert the anti-inflammatory effect in psoriasis-like model in keratinocytes." (PMID 33986690, 2021). "Collectively, these findings indicate that the biotechnologically produced LV extract resolved psoriasis-like inflammation in human keratinocytes by interfering the JAK2/STAT1 signaling pathway and its effectiveness is due to its high content of RA (10%)." (PMID 33986690, 2021).
psoriasis (continued). "In summary, our findings demonstrate that the biotechnologically produced LV extract diminished psoriasis-like inflammation in human keratinocytes by interfering the JAK2/STAT1 signaling and its effectiveness is due to the high content of RA." (PMID 33986690, 2021). "STAT1 has also been indicated as a potential target in the treatment of psoriasis, which is a chronic skin diseases." (PMID 34073305, 2021). "The STAT1, STAT3 and NF-κB are known to play a key role of the transcriptome network implicated in the psoriasis development." (PMID 34834106, 2021). "In the skin network, we identify KDs such as ICAM1, IL15, STAT1, TNFAIP3, and GRB2 to be the network hubs connecting numerous genes in the psoriasis-associated supersets." (PMID 30642337, 2019). "Among the KDs that are known psoriasis genes, STAT1 from IL23/IL17 pathway and cytokine-cytokine receptor interaction appears to be a KD in both the blood and skin networks." (PMID 30642337, 2019). "The psoriasis-associated supersets were also found to be closely linked in the blood network via KDs such as CTSH, IL1B, STAT1, and IFITM2." (PMID 30642337, 2019). "The JAK1/JAK2/STAT1 and JAK1/TYK2/STAT3 pathways triggered by IFN-γ and IL-22, respectively, are aberrantly activated in psoriasis, as highlighted by the peculiar STAT1 and STAT3 signatures in psoriatic skin lesions." (PMID 30581877, 2018). "Regarding STATs, qPCR results indicated overexpression of STAT3 (p = 0.052) and STAT1 (p = 0.005) in psoriasis." (PMID 27711196, 2016). "We have highlighted one DEM, designated “STAT1-57”, which is induced by multiple cytokines and activated in psoriasis epidermis, as well as certain skin cancers, but is repressed with biologic therapies (i.e., etanercept, efaluzimab and ixekizumab)." (PMID 24260178, 2013). "This corresponds to the decrease in STAT1 expression in psoriasis lesions observed after UVB phototherapy by transcriptome profiling, although this finding could not be attributed to a particular cell type in the whole skin biopsies." (PMID 40243413, 2025). "Herein, we present a patient with recalcitrant psoriasis where treatment with guselkumab (anti–IL-23) could have led to the development of LP that may reflect a shift and/or expansion of STAT1 pathway effector cytokines." (PMID 40948686, 2025). "Additionally, proteins such as MAPK3, MAPK14, JAK2, and STAT1 were identified as having a direct impact on psoriasis-related disease proteins." (PMID 39590306, 2024). "The JAK/STAT1 signaling pathway is involved in a range of autoimmune diseases, including rheumatoid arthritis, inflammatory bowel disease, hepatitis, and psoriasis." (PMID 36838711, 2023). "Overexpression of the active form of STAT3 in psoriasis leads to increased numbers of IL-17–producing cells and mediates the production of IL-23, resulting in the amplification of the Th17 pathway, while STAT1 stimulates the upregulation of keratin 17 expression." (PMID 37597582, 2023). "Genome-wide association studies (GWAS) have established a relationship between the JAK-STAT pathway and IMIDs, For example, JAK2, Tyk2, STAT1, STAT3, STAT4, and IBD; TyK2, TAT1, SLE; TyK2, STAT4, RA; and TyK2, STAT3, and psoriasis are closely linked to the JAK-STAT pathway." (PMID 37351513, 2023). "In addition to STAT3, STAT1 can also trigger tumorigenesis in psoriasis patients, together with other genes that participate in the cell cycle events." (PMID 36497125, 2022). "Additionally, STAT1 expression is elevated in lesion psoriatic skin, suggesting that the JAK/STAT signalling pathway is associated with psoriasis." (PMID 34080300, 2021). "Particularly, PRKCQ‐AS1, SH3PXD2A‐AS1 and CERNA2 are positively correlated to STAT1, indicating that the up‐regulated lncRNAs may participate in the progression of psoriasis through fine‐tuning the regulation of IFN‐γ signalling pathway." (PMID 34080300, 2021).